PNMT (phenylethanolamine N-methyltransferase)
Description:
Catalyzes the transmethylation of nonepinephrine (noradrenaline) to form epinephrine (adrenaline), using S-adenosyl-L-methionine as the methyl donor. Other substrates include phenylethanolamine and octopamine. Also methylates normetanephrine (By similarity).
Synonyms: PNMTase; PENT
Tractability: Small molecule: a structure with a bound ligand is known; a high-quality ligand is known; it has a high-quality binding pocket; it belongs to a druggable protein family. PROTAC: a small molecule that binds it is known.
Target class: Enzyme; Transferase
Gene: Protein-coding gene on chromosome 17 (39,667,981 to 39,670,475, forward strand). Ensembl gene ENSG00000141744.
Pathways (Reactome):
Metabolism: Catecholamine biosynthesis
Gene Ontology:
Molecular function: phenylethanolamine N-methyltransferase activity; protein binding; methyltransferase activity
Biological process: catecholamine biosynthetic process; epinephrine biosynthetic process
Cellular component: cytosol
Genetic constraint (gnomAD): Loss-of-function variants: 23 observed, 22.34 expected, observed/expected ratio (o/e) 1.03, 90% interval 0.74 to 1.46. The upper end of that interval is the gene's LOEUF score, 1.46, which puts it in group 6 of 6, group 1 being the genes least tolerant of losing a copy. Missense variants: 378 observed, 357.64 expected, observed/expected ratio (o/e) 1.06, 90% interval 0.97 to 1.15. Synonymous variants: 167 observed, 157.98 expected, observed/expected ratio (o/e) 1.06, 90% interval 0.93 to 1.2.
Homologues: Orthologues: chimpanzee PNMT (99% identical), macaque PNMT (95% identical), dog PNMT (89% identical), pig PNMT (88% identical), rabbit PNMT (87% identical), mouse Pnmt (84% identical), rat Pnmt (84% identical), guinea pig PNMT (78% identical), tropical clawed frog pnmt (59% identical), Caenorhabditis elegans anmt-2 (23% identical), Caenorhabditis elegans anmt-3 (22% identical), Caenorhabditis elegans anmt-1 (19% identical), and 1 more. Paralogues in human: NNMT (34% identical), INMT (34% identical).
Diseases named in the same sentence as PNMT in open-access papers:
PNMT is named in the same sentence as 31 diseases in open-access papers, as found by Europe PMC text mining. Sharing a sentence is not in itself a finding about the gene and the disease. The quoted sentences say what the papers report.
Hypertension (10 papers, 2007 to 2024). The presence of chronic increased pressure in the systemic arterial system. "Previous studies have associated polymorphisms of the PNMT gene to catecholamine levels and hypertension." (PMID 36517512, 2022). "PNMT, which catalyzes the synthesis of epinephrine from norepinephrine, displayed the strongest association with hypertension (Pgene<0.004), DBP (Pgene<0.004), and SBP (Pgene<0.009) of any gene in the ADRA1 pathway." (PMID 22615923, 2012). "Multiple genes within the ADRA1 pathway were associated with hypertension and DBP, with the PNMT gene and the ADRA1B gene displaying the strongest associations." (PMID 22615923, 2012). "In the present study, the decline in miR-375 with a target sequence in the DBH and PNMT mRNAs could have contributed to the worsening hypertension in the IH condition induced by the up-regulation of the DBH and PNMT mRNAs." (PMID 35682548, 2022). "SNPs in ADRA1B and PNMT have not previously been linked to hypertension in a genome-wide association study, but both genes have shown associations with hypertension through linkage or model organism studies." (PMID 22615923, 2012). "Within the ADRA1 pathway, the genes PNMT (hypertension Pgene<0.004, DBP Pgene<0.004, and SBP Pgene<0.009, and ADRA1B (hypertension Pgene<0.005, DBP Pgene<0.02, and SBP Pgene<0.02) displayed the strongest associations." (PMID 22615923, 2012). "Of note, PNMT, MPZ, RAB3C, and CD36 are found to differentially expressed and can be potential targets for AMH, providing a theoretical basis for mechanistic exploration of AMH along with hypertension." (PMID 36583008, 2022). "EGCG-mediated increases in PNMT protein do not correlate with elevated blood pressure and the development of hypertension, likely due to regulation of enzymes upstream of PNMT in catecholamine biosynthesis, providing less substrate for catalysis." (PMID 33805403, 2021).
breast carcinoma (7 papers, 2006 to 2023). "Previous reports have identified co-amplification of GRB7, PNMT, and TCAP in HER2-positive breast cancer, specifically due to their location in the 17q12 region." (PMID 33087122, 2020). "GRB7, PNMT, and TCAP are expected to be amplified in HER2-positive breast cancers due to their location within the HER2 amplicon on the long arm of chromosome 17 (17q12)." (PMID 33087122, 2020). "Of these candidate oncogenes, several, notably TOP2A, PNMT and UBE2C, have appeared in prognostic gene expression signatures, thus re-emphasizing their important role in breast cancer." (PMID 17925008, 2007). "Gene amplification and coexpression of PNMT and ERBB2 have been observed in breast cancer patients." (PMID 36984849, 2023). "For example, STARD3, PNMT, CAB2, C17ORF37 and GRB7 show a significant correlation between amplification status and expression level, and STARD3, PNMT, CAB2, GRB7 and ZNFN1A3 could all be biologically relevant to breast cancer." (PMID 17117180, 2006).
neuroblastoma (7 papers, 2012 to 2025). Neuroblastoma (NB) is the most common solid, extracranial childhood tumor. "We recently reported that IH increases renin expression in juxtaglomerular cells, as well as the expression of dopamine β-hydroxylase and phenylethanolamine N-methyltransferase in catecholamine-synthesizing neuroblastoma cells, causing SAS patients to become hypertensive." (PMID 35955916, 2022). "In this study, the gene expression of DBH and PNMT was increased via the down-regulation of the miR-375 level in the IH-treated neuroblastoma cells." (PMID 35682548, 2022). "Thus, we exposed catecholamine-synthesizing neuroblastoma cells to IH in the present study and found that IH exposure induced increases in the DBH and PNMT mRNA levels in human neuroblastoma cells." (PMID 35682548, 2022). "Taken together, IH upregulates the mRNA levels of Ren and Cd38 in JG cells via the downregulation of miR-203-mediated mRNA degradation and the mRNA levels of DBH and PNMT in neuroblastoma cells via the inhibition of miR-375-mediated mRNA degradation, which may contribute to hypertension." (PMID 36361741, 2022). "The low sensitivity of E and NM can be explained by the lack of phenylethanolamine-N-methyltransferase (PNMT) expression in neuroblastomas." (PMID 40520658, 2025). "Of note, the PNMT gene is not or weakly expressed at the mRNA level in the series of neuroblastoma cell lines studied by Boeva and colleagues, and another study showed that PNMT was not present in any of the analyzed neuroblastoma cell lines (n = 25), as evaluated by Western blot." (PMID 34200747, 2021). "Hence, the exact nature of the neuroendocrine cells detected in lobular neuroblastomas has not been established, although the adrenal chromaffin marker gene PNMT is not expressed, ruling out a neuroblastoma-to-pheochromocytoma conversion pathway." (PMID 22376239, 2012). "There is a similar lack of overlap between PNMT and EPAS1 expression in neuroblastoma as in the developing adrenal medulla, potentially reflecting a N-type like, rather than E-type like, chromaffin identity in cells with elevated EPAS1 levels." (PMID 41118218, 2025).
pheochromocytoma (6 papers, 2016 to 2024). "It is known that pheochromocytomas associated with MEN 2 express the phenylethanolamine‐N‐methyltransferase (PNMT) enzyme, which converts norepinephrine to epinephrine." (PMID 38747189, 2024). "As a kinase signalling pheochromocytoma, it represents a more ultimate cell differentiation with expression of phenylethanolamine N-methyltransferase (PNMT) as the most prominent characteristic, allowing synthesis of epinephrine from norepinephrine." (PMID 33815275, 2021). "To better characterize the function of PNMT in PCC/PGL, we analyzed a large (125 samples) public PCC/PGL microarray expression profile dataset (GSE19987) with a variety of mutations in pheochromocytoma susceptibility genes such as RET, VHL, SDHB and SDHD." (PMID 27007161, 2016). "Finally, kinase signaling exhibited the highest expression of PNMT (phenylethanolamine N-methyltransferase), an enzyme known to convert norepinephrine to epinephrine and according to that, was found mainly in pheochromocytomas." (PMID 33810219, 2021). "The overexpression of PNMT was responsible for the significantly elevated epinephrine of the rare Case 1 with ectopic ACTH and CRH secretory pheochromocytoma." (PMID 34905486, 2021).
adrenal tumors (2 papers, 2015 to 2021). "The converting enzyme of normetanephrine andmetanephrine (phenylethanolamine -N- methyltransferase) is only active in adrenal tumors." (PMID 26600911, 2015).
asthma (2 papers, 2012 to 2021). "The strongest expression–trait associations for asthma were observed at PNMT (phenylethanolamine N-methyltransferase) on chromosome 17 (the strongest association at the adipose visceral omentum, PTWAS = 6.58 × 10−46), which catalyzes the synthesis of epinephrine from norepinephrine." (PMID 35126453, 2021). "The adrenal medullary chromaffin cells (AMCC) transition to the neuronal phenotype is known to occur in asthma, as evidenced by degranulation of chromaffin granules, decline of epinephrine (EPI) and phenylethanolamine-n-methyl transferase (PNMT), and obvious alterations in cellular architecture." (PMID 22474509, 2012).
gastric cancer (2 papers, 2010 to 2018). A primary or metastatic malignant neoplasm involving the stomach. "For example; in gastric cancers the frequently amplified 17q12-q21 region contains genes such as ERBB2, GRB7, JUP, PERLD1, PNMT, PPP1R1B, STARD3, and TOP2A." (PMID 20187983, 2010).
hypoglycaemia (2 papers, 2015 to 2024). "In addition to TH, three episodes of insulin-induced hypoglycaemia also increased AADC and PNMT protein expression, while both recurrent glucoprivation and hypoglycaemia increased DBH protein expression within the adrenal gland." (PMID 38392992, 2024). "Whereas PNMT mRNA levels in response to subsequent hypoglycaemia was not affected in rats exposed to either one or two episodes of hypoglycaemia per day for 3 days." (PMID 38392992, 2024).
paraganglioma (2 papers, 2012 to 2016). A benign or malignant neoplasm arising from paraganglia located along the sympathetic or parasympathetic nerves. "Except for the paragangliomas that originate from the organ of Zuckerkandl and produce various catecholamines, functional paragangliomas in various body sites secrete only noradrenaline owing to a lack of phenylethanolamine N-methyltransferase in those areas." (PMID 22716303, 2012).
Anxiety (1 paper, 2026). Intense feelings of nervousness, tension, or panic often arise in response to interpersonal stresses. "GO analysis further highlighted alterations in key regulators of anxiety-related neurotransmission, including neuropeptide Y and L-DOPA receptor activities, as well as phenylethanolamine N-methyltransferase activity." (PMID 41536523, 2026).
chromaffin tumors (1 paper, 2022). "The downregulation of the phenylethanolamine N-methyltransferase (PNMT) could explain the higher levels of norepinephrine in metastatic disease or Von Hippel-Lindau (VHL)-related chromaffin tumors." (PMID 36009360, 2022).
congestive heart failure (1 paper, 2025). Failure of the heart to pump a sufficient amount of blood to meet the needs of the body tissues, resulting in tissue congestion and edema. "Because PNMT (phenylethanolamine-N-methyl transferase) is a SAM-dependent enzyme that converts norepinephrine to epinephrine, the low SAM levels in MDS cells may partly contribute to increased NE secretion and result in congestive heart failures." (PMID 39508990, 2025).
neuroendocrine tumors (1 paper, 2025). "Furthermore, PNMT could also be involved in neuroendocrine tumors through epigenetic mechanisms, highlighting its potential as a therapeutic target for diseases associated with adrenergic signaling dysregulation." (PMID 41181152, 2025).
Obesity (1 paper, 2013). Accumulation of substantial excess body fat. "QTL for NVD was homologous with HSA 17q21 regions which contained many obesity candidate genes including PPY, PON1 and 2, GAST, PNMT, STAT3 and HCRT." (PMID 23977060, 2013).
parasitic infections (1 paper, 2025). "For instance, certain tetrahydroisoquinoline (THIQ) compounds inhibit phenylethanolamine N-methyltransferase (PNMT), suggesting a potential mechanism against parasitic infections via disruption of essential parasite enzymes." (PMID 41156679, 2025).
pulmonary fibrosis (1 paper, 2023). Chronic progressive interstitial lung disorder characterized by the replacement of the lung tissue by connective tissue, leading to progressive dyspnea, respiratory failure, or right heart failure. "According to the results of qRT-PCR, the expression levels of ENPP3, PDE7B, and ENTPD1 were elevated, while the expression levels of PNMT, GPX3, and POLR3H were decreased in the lung tissues of bleomycin-induced pulmonary fibrosis mice compared with the sham group." (PMID 36923791, 2023).
Stroke (1 paper, 2012). Sudden impairment of blood flow to a part of the brain due to occlusion or rupture of an artery to the brain. "A locus on rat chromosome 10 mapping to the human PNMT locus on chromosome 17q21–q22 has been associated with blood pressure regulation in the stroke-prone spontaneously hypertensive rat." (PMID 22615923, 2012).
tumor (14 papers, 2012 to 2024). "Pseudohypoxic tumours are usually noradrenergic due to low or lost expression of the enzyme phenylethanolamine- N-methyltransferase (PNMT) that converts norepinephrine into epinephrine, which may be a sign of dedifferentiation." (PMID 33138083, 2020). "Low PNMT mRNA levels in PCCs might reflect an insufficient concentration of plasma cortisol in the artery supplying the tumor." (PMID 27007161, 2016). "We examined PNMT-, NDUFC2-, and MTAP-associated outlying genes that were part of metabolic pathways and also ERBB2-, PAK1-, and CDKN2A-associated outlying genes that were related to the oncogenic/tumor suppressor pathways." (PMID 23383675, 2012). "In addition, we show here that PNMT gene encoding for the enzyme catalysing the conversion of noradrenaline to adrenaline is hypermethylated and downregulated in VHL tumours, suggesting that epigenetic silencing of this gene explains the noradrenergic phenotype of both VHL- and SDHx-mutated tumours." (PMID 25625332, 2015). "It is worth noting that many genes were dramatically upregulated specifically in ACTH+&CRH + pheochromocyte when compared with the other tumor cell types, such as GAL, POMC, PNMT, and CARTPT." (PMID 34905486, 2021). "TCGA database analysis revealed that MNX1 expression was significantly higher compared with that in normal tissue in the pathological and clinical tumor stages (T stage), whereas PNMT expression was not significantly different in the pathological and T stages compared with that of normal tissue." (PMID 38203393, 2023).
cancer (5 papers, 2018 to 2025). A tumor composed of atypical neoplastic, often pleomorphic cells that invade other tissues. "Thus, the coexpression pattern between ERBB2 and other genes, such as PGAP3, STARD3, and PNMT, may be a marker of cancer, and site mutations in the interaction anchors or dysregulation in interactions related to ERBB2 may be a new target for cancer studies." (PMID 36702236, 2023). "With respect to genes CDK12 (CRKRS), CWC25 (CCDC49), GRB7, MIEN1 (C17orf37), PNMT and SIRT3, they have been shown to be linked to HER2 receptor and cancer." (PMID 37096121, 2023). "However, the role of genes such as PNMT, TCAP, and PPP1R1B in BC and other cancers is still not well defined, requiring further research to understand their potential as biomarkers or therapeutic targets." (PMID 40136626, 2025).
benign tumors (1 paper, 2016). "The present study demonstrates that PNMT downregulation correlates with malignancy in PCC/PGL and identifies PNMT as one of the most differentially expressed genes between malignant and benign tumors." (PMID 27007161, 2016). "This is the first demonstration of the association between PNMT downregulation and PCC/PGL malignancy in humans, and our findings identify PNMT as one of the most differentially expressed genes between malignant and benign tumors." (PMID 27007161, 2016). "The PNMT enzyme plays a key role in adrenal medulla function, and its expression was downregulated in malignant PCC/PGL compared to benign tumors." (PMID 27007161, 2016).
PNMT also shares sentences with these, for which no sentence is quoted: prostate carcinoma (2 papers); Alzheimer disease (1); colorectal cancer (1); depression (1); essential hypertension (1); ischemia (1); malignant pheochromocytoma (1); metastatic disease (1); neurological disorders (1); panic disorder (1); viral infection (1).